INS (insulin)
Diseases named in the same sentence as INS in open-access papers (continued):
Sharing a sentence is not in itself a finding about the gene and the disease.
Hyperglycemia (continued). "Insulin therapy should be delayed until there is no significant decrease in hyperglycemia as in classical HHS, starting at half the typical 0.1 unit/kg/h insulin infusion dose used in DKA, with glucose and saline fluid adjustments based on the hyperglycemia and electrolyte status." (PMID 38002864, 2023). "With advancing pregnancy insulin sensitivity decreases, leading to manifest hyperglycemia in patients who do not adequately compensate impaired insulin action by increased insulin release from the pancreatic β-cells." (PMID 35663318, 2022). "In the present study, the different medicaments revealed improvement in the islets morphology and an increase in the insulin content of β-cells of the pancreatic islets, especially with GLB+VGN-20 treatment, which appeared in the form of reducing the hyperglycemia in this group." (PMID 36555498, 2022). "Exposure to either supraphysiological high- or low-dose PBDEs or HBCD consistently led to fasting hyperglycemia in chow-fed male rodents but no change in glucose tolerance or insulin sensitivity." (PMID 35156417, 2022). "Hyperinsulinemia with simultaneous hyperglycemia has no influence on plasma ghrelin at concentrations seen in insulin‐resistant patients, according to a prior study, but only at pharmacological insulin doses." (PMID 36305681, 2022). "The purpose of STZ induced diabetic rat model used in this due to lineaments such as stable hyperglycemia without insulin requirement to survive and response to glibenclamide." (PMID 35620596, 2022). "Non-Hispanic Black adults (OR, 2.48; 95% CI, 1.71-3.61) and Mexican American adults (OR, 2.29; 95% CI, 1.32-3.98) using insulin were more likely to have severe hyperglycemia compared with non-Hispanic White adults." (PMID 36538330, 2022). "We observed that WWOX silencing significantly increased glucose uptake in normoxia normoglycemia and reduced glucose uptake in hypoxia hyperglycemia conditions in the absence of insulin." (PMID 35328751, 2022). "Women with PCOS are more likely to have postprandial hyperglycaemia owing to the peripheral insulin resistance rather than fasting hyperglycaemia due to intact endogenous glucose production mechanism." (PMID 36159086, 2022). "Hyperglycaemia in TLR2−/− mice occurred despite a marked increase in basal serum insulin levels at 9 months of age, indicating that TLR2−/− mice were becoming more resistant to insulin than their WT counterparts with age." (PMID 36555322, 2022). "Several trials have tested the effects of insulin administration in the absence of hyperglycemia, but the evidence is inconclusive." (PMID 35358060, 2022). "Metformin, a common pharmaceutical for hyperglycemia and T2D, led to similar increases in glucose uptake in the presence or absence of insulin; indicating that metformin does not impact insulin responsiveness in peripheral muscle tissue." (PMID 36435511, 2022). "We are aware that we should not explain increased content of blood insulin and amelioration of hyperglycemia in APH-treated diabetic rats only by the generation of new extra-islet IPCs." (PMID 35457103, 2022). "The disease at earlier stages frequently goes undiagnosed because classic symptoms develop gradually as hyperglycemia develops, and insulin levels in such patients are often normal or elevated." (PMID 35620114, 2022). "T1DM, being a consequence of autoimmune β-cell destruction, results in hyperglycaemia, with a relative absence of insulin production." (PMID 36144236, 2022). "When leptin administration was stopped, hyperglycemia was quickly reestablished in the absence of changes in insulin, indicating the central effect of leptin on the modulation of glucose metabolism." (PMID 35052794, 2022). "Of interest, the effects on hyperglycemia of these antidiabetic drugs are not always sufficient to preserve insulin secretory capacity in the db/db mouse, most likely due to the severity of this model." (PMID 35657616, 2022).
Hyperglycemia (continued). "Moreover, especially the time with hyperglycemia and the AGP interdecile range were reduced considerably, indicating the effect of individualized education on the appropriate dose of prandial insulin, which prevented wide glycemic excursions." (PMID 36506077, 2022). "Reduced lean body mass and mitochondrial dysfunction contributed to the increased myogenic insulin resistance of non-obese hyperglycemia." (PMID 35884949, 2022). "In cell types exposed to hyperglycemia that are highly permeable to glucose in the absence of insulin signaling, the glycolytic triose phosphates glyceraldehyde-3-phosphate and dihydroxyacetone phosphate accumulate." (PMID 36135209, 2022). "Glutamatergic signaling decreased with long-term hyperglycemia and did not normalize with insulin-induced normoglycemia." (PMID 36552776, 2022). "In the early stage of abnormal insulin secretion, repaglinide can minimize the incidence of postprandial hyperglycemia, without impact on the cardiovascular system, but reduces the risk of cardiovascular damage." (PMID 35371345, 2022). "Patients with T1DM require overlapping insulin when PN is interrupted; otherwise hyperglycemia will develop if no insulin is administered and the shorter half-life of IV insulin increases the risk of ketosis." (PMID 36992742, 2022). "The majority of newly diabetic NOD mice treated with the major target determinant insulin B9-23/alum IP or with soluble insulin B9-23 intradermally, in combination with low-dose oral GABA, reverted to hyperglycemia within 5 weeks; however, about 15% remained disease-free for up to 32 weeks." (PMID 35406645, 2022). "A primary risk factor for DR is uncontrolled levels of blood sugar, due to a lack of insulin, or impaired insulin sensitivity leading to hyperglycemia." (PMID 36686464, 2022). "While the GLP-1 reduces blood glucose by several mechanisms, including stimulating insulin secretion and suppressing glucagon release during hyperglycemia, GIP stimulates insulin release during hyperglycemia, but it also stimulates glucagon release during hypoglycemia." (PMID 36289697, 2022). "We demonstrated here that this is also the mechanism underlying early loss of insulin content in a mouse model of monogenic KATP-GOF induced NDM in the absence of hyperglycemia-induced insulin hypersecretion and β-cell exhaustion." (PMID 35180212, 2022). "In the event of hyperglycemia during closed-loop, the algorithm automatically increases insulin delivery to manage this; however, delays in subcutaneous insulin absorption can mean that target glucose levels are not reached immediately." (PMID 32914648, 2022). "The present study confirms the feasibility of implementing an easier, safer and equally effective treatment modality using basal insulin plus DPP4-i, compared to the classic basal–bolus insulin regimen for the management of hyperglycemia in hospitalized older adults." (PMID 35628938, 2022). "Within two hours after injections, higher blood glucose levels (hyperglycemia) were observed in mice that received anti-insulin IgMlow, while anti-insulin IgMhigh did not alter blood glucose and was able to protect insulin from IgG-dependent degradation." (PMID 36341420, 2022). "Out of the nine salivary cytokines we analyzed, CRP and insulin levels strongly differentiated obese vs. non-obese youths and individuals with intermediate hyperglycemia vs. those with normal glycemia." (PMID 35757631, 2022). "The fasting blood glucose level of the first dog reached 40.00 mmol/L without the support of exogenous insulin, and thus, this level of hyperglycemia is challenging to reverse through the transplantation of ra-βCs." (PMID 35902971, 2022). "GlyNAC supplementation significantly lowered both fasting insulin concentrations and IR, without lowering fasting hyperglycemia or HbA1c." (PMID 35052658, 2022). "For hyperglycemia after SAH, the effects of insulin treatment are not satisfied even with a high risk of hypoglycemia." (PMID 36062190, 2022).
Hyperglycemia (continued). "An INS reservoir (GOx, CAT, and BSA) and could counter hyperglycemia in diabetic rats over a 1-week period." (PMID 36246353, 2022). "The postprandial hyperglycemia, evaluated by the single glucose test 1 and 2 h after the HGI and LGI meals, was not statistically significant in our study, even if a difference was detected when the two insulin formulations were used." (PMID 36014822, 2022). "β-sitosterol, an effective anti-oxidant and anti-hyperlipidemia plant sterol in C. sinensis, was reported to lower lipid levels, restore insulin sensitivity, and activate insulin receptors and GLUT4 in adipose tissue and eventually exert anti-hyperglycemia activity in diabetic rats." (PMID 35645822, 2022). "This means that the blood plasma insulin level of individuals with T2D can be in the normal range, but the insulin is not able to stimulate glucose utilization by the cells, leading to hyperglycemia." (PMID 35562924, 2022). "Furthermore, it was suggested that this mechanism is common to both the anti-apoptotic and insulin-sensitizing action of AMPK in hyperlipidemia and hyperglycemia." (PMID 36551937, 2022). "Hyperglycemia was more common in the IVIG plus corticosteroids group compared with the corticosteroids group; among 40 patients with hyperglycemia, 4 patients (10%) required inpatient insulin, which was continued postdischarge in 1 patient." (PMID 35344042, 2022). "In contrast, TgH mice had lower steady state plasma insulin levels, which may lead to HFD-induced hyperglycemia in TgH mice." (PMID 35831364, 2022). "These individuals initially present an acute form presentation with severe hyperglycemia and ketosis due to a lack of response and stimulus of β-cell insulin secretion." (PMID 35743358, 2022). "Hyperglycemia is an independent risk factor for the poor prognosis in patients with traumatic brain injury (TBI), and stress-induced impaired insulin function is the major factor of hyperglycemia in non-diabetic patients with TBI." (PMID 35968315, 2022). "Hyperglycemia in GDM occurs when an adequate increase in insulin secretion does not accompany the IR." (PMID 36992779, 2022). "The SARS-CoV-2 infection resulted in alterations in the glucose–insulin axis that led to hyperglycemia, hyperinsulinemia and IR in patients with and without comorbidities." (PMID 35326383, 2022). "At the same time, the ability of insulin to suppress glucose and VLDL production in the fatty liver is impaired, resulting in mild hyperglycemia and stimulation of insulin secretion, hyper-triglyceridaemia, and low HDL cholesterol concentration, which are also components of MetS." (PMID 35571045, 2022). "It is a group of metabolic diseases represented by hyperglycemia stemming from either the lack of insulin action or insulin secretion or both." (PMID 35745591, 2022). "An early delivery at 38 weeks or treatment of maternal hyperglycaemia with insulin can be considered when a foetus has not inherited the mutation." (PMID 35445424, 2022). "The results suggest that infection with SARS-CoV-2 in patients with and without comorbidities results in alterations in the glucose–insulin axis which leads to hyperglycemia, hyperinsulinemia and IR." (PMID 35326383, 2022). "In fact, hyperglycemia in Group 1 was almost always rapidly reversible, most often without the need for insulin treatment." (PMID 36038896, 2022). "Some researchers believed that hyperglycemia after nocturnal hypoglycemia was due to the lack of insulin rather than hormonal counter-regulation." (PMID 36237834, 2022). "It is possible that the inability of GIP to increase insulin secretion during hyperglycemia is primarily due to the lack of glucose amplification of insulin release in DM 2 patients." (PMID 35205155, 2022). "Due to its role in both glucose metabolism and insulin secretion, it is no surprise that hyperglycemia and hypoglycemia constitute the more common phenotypes of GCK mutations." (PMID 36361703, 2022).
Hyperglycemia (continued). "When β cells of Gcgr -/- mice were destroyed by streptozotocin (STZ) and insulin secretion was inhibited, animals did not develop hyperglycemia, suggesting that Gcgr -/- mice do not develop T1D, even under a state of insulin deficiency." (PMID 35784565, 2022). "In T1DM models, adenoviral-induced hyperleptinemia corrected severe hyperglycemia, despite the absence of insulin, via suppressing glucagon action in the liver and enhancing the insulinomimetic action of the insulin-like growth factor in muscle." (PMID 35052794, 2022). "They phosphorylated AKT and did not develop life-threatening hyperglycemia, nor did they become catabolic even though these mice lacked fully processed insulin." (PMID 35963866, 2022). "ECs are more susceptible to hyperglycemia-induced damage than other cell types, since glucose enters them through the GLUT-1 transporter independently from insulin, largely independent of its extracellular concentrations." (PMID 36140374, 2022). "Instead of a single isolated compound, the methanolic extract of Halophila beccarii itself acts as a prominent drug to reduce hyperglycemia without side effects as an insulin-sensitizer." (PMID 36042748, 2022). "For all groups, serum OGF levels were elevated within 4 weeks of induction of hyperglycemia, suggesting that insulin did not protect against the dysregulation of the OGF-OGFr axis." (PMID 36274979, 2022). "If the fall in insulin concentration was due to β-cell failure, and not in response to a drop in IR, there would have been a rise in hyperglycemia, but this did not occur." (PMID 35052658, 2022). "It was reported that C‐phycocyanin, a kind of blue protein isolated from Spirulina platensis, can ameliorate hyperglycemia through inhibiting hepatic gluconeogenesis and increasing glycogen synthesis due to activating Akt and AMPK in insulin resistance hepatocytes." (PMID 35844917, 2022). "Dyslipidemia is due to insulin dysregulation and hyperglycemia, and omega-3 PUFAs do not affect these processes." (PMID 36225205, 2022). "Hyperglycaemia can be modelled in in rodents with STZ, a diabetogenic drug that is toxic to insulin‐producing pancreatic β cells via the alkylation of β‐cell DNA, thus impairing insulin secretion and inducing chronic hyperglycaemia." (PMID 35128745, 2022). "Insulin is no longer produced, and insulin-stimulated glucose uptake is reduced, resulting in persistent hyperglycemia." (PMID 36497026, 2022). "This vicious cycle continues until pancreatic beta-cell activity can no longer adequately meet the insulin demand created by insulin resistance, resulting in hyperglycemia." (PMID 35734406, 2022). "We excluded a role for the pentose phosphate pathway as inhibition of 6-phosphogluconate dehydrogenase with 6-aminonicotinamide (6-AN) did not prevent the effects of hyperglycaemia on insulin secretion, insulin content or gene expression." (PMID 36376280, 2022). "All doses of COSM could improve the high insulin level induced by an HFHSD, and thus, COSM could improve IR and hyperglycemia." (PMID 35736186, 2022). "Then, in the second trimester of gestation, when the fetal pancreas becomes able to secrete insulin and begins to respond to hyperglycemia and releases insulin autonomously, regardless of glucose stimulation, excessive secretion of this hormone occurs." (PMID 36275053, 2022). "In the liver compartment of our chips, hyperglycemia induced AKT phosphorylation and resulted in rapid induction of de novo lipogenesis, as well as inhibition of gluconeogenesis, characteristic of the physiological liver insulin response." (PMID 36285680, 2022). "This combination creates a model ofinsulin-deficient – but not insulin-resistant – T2DM, characterizedby stable, moderate hyperglycemia associated with an approximately 60% loss ofβ-cell function." (PMID 36348712, 2022).
Hyperglycemia (continued). "Although the detection of insulin differed between the two criteria, both of them included insulin as PIM due to higher risk of hypoglycemia without improvement in hyperglycemia management." (PMID 36249753, 2022). "MODY classically presents before 25 years of age in individuals with hyperglycemia who do not require insulin, and appears to be inherited in an autosomal dominant manner." (PMID 35246208, 2022). "In GDM, β-cell insulin secretion is not sufficient to compensate for the insulin resistance of pregnancy, resulting in hyperglycemia during pregnancy." (PMID 35457285, 2022). "In contrast, insulin was used in some patients with hyperglycemia or neonatal diabetes, and all of them did not have symptomatic hypoglycemia." (PMID 35757134, 2022). "For women who are not pregnant, hyperglycemia results from a defect in either insulin secretion or insulin sensitivity, which supports the possibility of the physiologic heterogeneity of GDM." (PMID 36246890, 2022). "In the future, using this model, preventive and therapeutic strategies for non-obese hyperglycemia will be studied, such as the use of growth hormone, whey protein, or Chinese medicine, and non-invasive insulin therapy." (PMID 35884949, 2022). "Compared to IFG, IGT presents severe transitory hyperglycemia, which may explain the higher GSH, SOD, nesfatin-1, insulin and HOMA-β levels in IGT than IFG in our study." (PMID 36045734, 2022). "In endothelial cells, insulin signaling that targets eNOS activity through the regulatory phosphorylation of this enzyme also appears to be impaired in hyperglycemia, although this issue was not thoroughly investigated." (PMID 36551937, 2022). "During the oGTT, as observed by the AUC, LP-F1 dams showed mild glucose intolerance (+10.21%; p < 0.05) and fasting hyperglycemia (+17.02%; p < 0.01), without differences in insulin sensitivity, as demonstrated by Kitt." (PMID 36704794, 2022). "We also evaluated whether adding 1-h PG significantly improves the prediction of hyperglycemia relapse compared to glucose levels at other time points during the OGTT and HbA1c levels at the time of insulin discontinuation." (PMID 35721763, 2022). "At which point during evolution insulin appeared as a necessary counterbalance to hyperglycemia is unclear; the fact is that, in the absence of insulin, mammalian control of glycemia is severely hampered." (PMID 35736456, 2022). "Previously, it was noted that post-exercise hyperglycemia was temporary; therefore, treating it with insulin was not recommended." (PMID 35345701, 2022). "Short-term mifepristone administration improves adipose and hepatic insulin sensitivity in obese individuals with hyperglycemia without hypercortisolism." (PMID 36158399, 2022). "First, it was found that as many as 19.40% of breast cancer patients who underwent ACT could develop hyperglycemia and exhibited a poor DFS; accordingly, the serum insulin level was observed to experience an elevation." (PMID 35715761, 2022). "Insulin-resistant subjects are largely determined by an increased postabsorptive (“basal”) hepatic glucose production (HGP) and a reduced ability of insulin to suppress HGP, which contributes to hyperglycemia." (PMID 36554057, 2022). "Current therapeutic strategies to manage hyperglycemia do not halt (or reverse) disease progression and may even cause undesirable adverse effects and comorbidities on their own, while treatment with insulin, sulfonylureas, and glinides may lead to weight gain." (PMID 34757591, 2022). "Type II (NIDDM) is a noninsulin-dependent diabetes mellitus in which the body tissues do not respond to insulin, resulting in hyperglycemia." (PMID 35685725, 2022). "The present study demonstrates that silencing of PVT1 did not significantly reduce hyperglycaemia in diabetic mice but did suppress the decline in insulin levels." (PMID 36359234, 2022).